STAT3 (signal transducer and activator of transcription 3)
Diseases named in the same sentence as STAT3 in open-access papers (continued):
Sharing a sentence is not in itself a finding about the gene and the disease.
ulcerative colitis (87 papers, 2009 to 2026). An inflammatory bowel disease involving the mucosal surface of the large intestine and rectum. "Balsalazide shows promise in inhibiting ulcerative colitis-related carcinogenesis through IL-6/STAT3 signaling pathway, though it has been linked to pericarditis in some studies." (PMID 39444551, 2024). "Many studies have investigated the associations between the signal transducer and activator of transcription 3 (STAT3) in the susceptibility to ulcerative colitis (UC) and Crohn's disease (CD)." (PMID 25286337, 2014). "It is worthy to mention that STAT3 rs2293152 polymorphism may be associated with the occurrence of ulcerative colitis and might be used as a predictive factor for ulcerative colitis." (PMID 30127739, 2018). "Indeed, the STAT3 rs744166 ‘A’ allele is a significant risk factor for Crohn’s disease and ulcerative colitis." (PMID 27258062, 2016). "2’-Fucosyllactose inhibits STAT3-related signaling pathways in colonic tissue by suppressing STAT3 phosphorylation and palmitoylation, ultimately repairing the intestinal mucosal barrier in ulcerative colitis and reducing inflammatory responses." (PMID 40959086, 2025). "Berberine nanoparticles, with an average hydrodynamic size of 220 nm (230.2 ± 18.1 nm) and a relatively similar particle size distribution of 0.22, decreased the inflammatory response in DSS-induced ulcerative colitis by inhibiting the NFkB/STAT-3 pathway." (PMID 40006007, 2025). "Our result seems also in parallel with an in vitro study, which was conducted on an acetic acid-induced ulcerative colitis model in rats and proved the inhibitory effect of nifuroxazide on STAT3/JAK2 signaling." (PMID 40925930, 2025). "In short, Rauwolfia polysaccharide can inhibit the progress of ulcerative colitis through NOS2-mediated JAK2/STAT3 pathway." (PMID 38626146, 2024). "Protein-protein interaction analysis has underscored the significance of hub genes, notably Stat3, Il1b, Mmp3, and Lgals3, in the progression of ulcerative colitis." (PMID 38308210, 2024). "Reportedly, STAT3 and p-STAT3 expression significantly increased in patents with ulcerative colitis and Crohn’s disease." (PMID 38042791, 2023). "Whereas, increased IL‐6 expression exacerbates the inflammatory response of macrophages through the JAK1/STAT3 pathway in mouse models of ulcerative colitis." (PMID 36794521, 2023). "STAT3 expression is induced by TNF-α, and STAT3 levels are increased in the tissues of ulcerative colitis and Crohn’s disease patients." (PMID 38091316, 2023). "GGQLD has been shown to alleviate ulcerative colitis by inhibiting the IL-6/JAK2/STAT3 signal transduction pathway and restoring the homeostasis of Th17 and Treg cells within colon tissues." (PMID 37370132, 2023). "MiR-222-3p targets SOCS1 to aggravate the inflammatory response by suppressing VDR and activating STAT3 signaling in ulcerative colitis." (PMID 35946880, 2022). "CA has been reported to be able to reduce the inflammatory response in ulcerative colitis by modulating the JAK2/STAT3 pathway." (PMID 35645793, 2022). "Previous studies have showed that overexpression of microRNA495 downregulated STAT3 to improve intestinal mucosal barrier function in ulcerative colitis." (PMID 35399629, 2022). "The expression of phosphorylated-STAT3, signal transducer and activator of transcription 3, cyclin D1, and suppressor of cytokine signaling 3 was significantly increased in mice of ulcerative colitis model group compared to the control group (P < .05)." (PMID 35946886, 2022). "Oroxylin A as the main component extracted from Scutellariae radix can decrease the expression of inflammatory cytokines IL-6 and IL-1β, and attenuated IL-6/STAT3 signaling pathway in ulcerative colitis mice." (PMID 34997010, 2022). "Aspirin remarkably decreased phosphorylated-STAT3, signal transducer and activator of transcription, and cyclin D1 expression compared with ulcerative colitis model group (P < .05)." (PMID 35946886, 2022).
ulcerative colitis (continued). "Serving as a vital inflammation pathway, IL-6/STAT3 signaling pathway had been reported to be activated to trigger inflammatory response of the body in ulcerative colitis." (PMID 34722512, 2021). "Our study is in agreement with a recent study that reported that nifuroxazide reduced colon ulcer in an acetic acid-induced ulcerative colitis model via modulating the IL-6/STAT-3/Wnt axis." (PMID 34833950, 2021). "Together, these results demonstrated that Rab27A plays a crucial role in ulcerative colitis progression through regulating the miR‐124‐3p/STAT3/RelA pathway." (PMID 32815642, 2020). "In ulcerative colitis, overexpression of STAT3 is common and leads to progression from ulcerative colitis to CRC." (PMID 30046565, 2018). "Ulcerative colitis (UC) is characterized by aberrant regulation of tight junctions (TJ), signal transducer and activator of transcription 3 (STAT3), and interleukin (IL)-8/18, which lead to intestinal barrier defects." (PMID 30241336, 2018). "Patients with ulcerative colitis exhibited persistently elevated expression of total STAT3 and p-STAT3, a phenomenon that was positively correlated with the degree of inflammation." (PMID 27657728, 2016). "Several reports show that IL-11 stimulate and accelerate the development of ulcerative colitis, promote the tumor progression by activating the STAT3 and suppress the antitumor immune response." (PMID 26528857, 2015). "Levels of phosphorylated signal transducer and activator of transcription 3(STAT3) regulated the MMP-9 gene in pediatric patients with ulcerative colitis." (PMID 24476461, 2014). "In a DSS-induced murine ulcerative colitis UC model, daily gavage with dehydrocostus lactone at 20, 15, and 10 mg/kg/d from day 4–17 significantly reduced inflammation and enhanced barrier function by suppressing the IL-6/STAT3 pathway." (PMID 41158126, 2025). "According to the study on ulcerative colitis model mice, curcumin inhibited the expression of Tfh cells related transcription factors Bcl-6 and p-STAT3, and significantly increased the protein levels of Blimp-1 and STAT3 in colon tissue, so as to achieve a therapeutic effect." (PMID 38051200, 2024). "For instance, miR-214 exacerbates kidney damage and inflammation induced by hyperlipidemic pancreatitis, it mediates perivascular fibrosis in hypertension and it is involved, together with IL-6/STAT3, in ulcerative colitis pathogenesis where its targeting reduces the severity of the disease." (PMID 36639824, 2023). "Aspirin inhibited carcinogenesis of intestinal mucosal cells in the ulcerative colitis model by inhibiting the interleukin-6/Janus kinase/signal transducer and activator of transcription 3 signaling pathway and promoted apoptosis, thereby suppressing proliferation." (PMID 35946886, 2022). "Furthermore, abnormalities in the signaling pathway with STAT3 have been found in both ulcerative colitis and Crohn’s disease, suggesting an important role in the progression of ulcerative colitis." (PMID 36358661, 2022). "Similar expression patterns were found in colon tissues of children with active ulcerative colitis (UC), where decreased levels of miR-124 appeared to enhance expression and activity of STAT3, which could induce inflammation and pathogenesis." (PMID 32903657, 2020). "Furthermore, we clarified that Rab27A stimulated the STAT3/RelA signalling pathway by binding with miR‐124‐3p to promote the progression of ulcerative colitis." (PMID 32815642, 2020). "Mechanistically, Rab27A could regulate the miR‐124‐3p/STAT3/RelA axis to promote apoptosis and ROS production in ulcerative colitis." (PMID 32815642, 2020). "This study was conducted in a mouse model of ulcerative colitis, and the impact of NO on STAT3 phosphorylation was investigated in LPS-activated macrophages but not in a tumor context or in T lymphocytes in whose activation STAT3 plays a key role." (PMID 32370259, 2020).
ulcerative colitis (continued). "Western blot analysis and qPCR analysis in IEC6 cells stimulated by IL-6 in vitro revealed that EHLJ7 could cooperate with butyrate to exert its anti-ulcerative colitis effect by inhibiting the activation of JAK2/STAT3/SOCS1 pathway." (PMID 32038241, 2019). "Furthermore, recent studies show that STAT3 activation is increased, and SOCS3 is silenced in tumors of patients with ulcerative colitis-associated and sporadic CRC." (PMID 20500855, 2010). "Therefore, we speculate that Rau can inhibit the progress of ulcerative colitis through NOS2-mediated JAK2/STAT3 pathway." (PMID 38626146, 2024). "Supplementation of IL-22 may be an effective treatment, and local IL-22 gene delivery improves intestinal inflammation by enhanced signal transducer and activator of transcription 3 (STAT3) activation within colonic epithelial cells in the murine model of ulcerative colitis." (PMID 34975838, 2021). "Allicin can regulate CD68, MPO, MDA, and inflammation factor expression to attenuate DSS-induced ulcerative colitis, and its mechanism may be related to the regulation of signal transducer and activator of transcription 3 (STAT3) and nuclear factor-κB (NF-κB) signaling pathway activity." (PMID 31139644, 2019). "We evaluated the efficacy of HCB-5300 and HCB-5400, novel selective STAT3 allosteric inhibitors, in a mouse model of dextran sulfate sodium (DSS)-induced ulcerative colitis." (PMID 41465408, 2025). "The molecular docking analysis revealed promising binding affinities of ten BRLE bioactive compounds against four key ulcerative colitis-related targets (EGFR, SRC, STAT3, and AKT1), with binding scores ranging from −6.5 to −9.1 kcal/mol." (PMID 41465478, 2025). "KEGG enrichment analysis also showed that these targets are mainly enriched in pathways related to inflammation, immunity, and tumors, such as JAK/STAT3, NF-κB, and TNF signaling pathways, which are related to the development of ulcerative colitis." (PMID 34211579, 2021). "In addition to the insights into the pathology of this disease, we found a new pathway in the mechanism of UC: Rab27A, by regulating miR‐124‐3p, can activate the STAT3/RelA signalling pathway, which may provide novel therapeutic approaches with great impact in ulcerative colitis." (PMID 32815642, 2020). "To further explore the relationship among SCFAs, JAK2, STAT3, and SOCS1 and the development of ulcerative colitis, we initially observed changes in inflammation-related indicators in vivo." (PMID 32038241, 2019). "We conclude that MRS has a protective effect on acetic acid-induced ulcerative colitis in mice via blocking the TLR4/NF-κB/MAPK signaling pathway and promoting the IL-10/JAK1/STAT3-mediated anti-inflammatory response." (PMID 31182999, 2019). "Molecular docking studies were performed to evaluate the binding affinity and interaction profiles of ten bioactive compounds from BRLE against the four key protein targets (EGFR, SRC, STAT3, and AKT1) identified through network pharmacology analysis for ulcerative colitis treatment." (PMID 41465478, 2025). "The data demonstrated that LREE could significantly inhibit the production of IL-6 and phosphorylation of STAT3, JAK1, JAK2 in ulcerative colitis model mice." (PMID 34093175, 2021). "The findings indicated that FS could modulate the progression of ulcerative colitis via multiple targets, with STAT3, EGFR, ESR1, PTGS2, NF-κB1 and JUN identified as the six key targets significantly involved in the pathogenesis and progression of ulcerative colitis." (PMID 40649400, 2025). "Moreover, we found that FLCWK significantly inhibited IL-6 and STAT3 mRNA expression in a rat model of ulcerative colitis, which may provide a theoretical pharmacodynamic basis for the enhancement of 5-FU efficacy in CRC by suppressing the IL-6/STAT3 pathway." (PMID 33082817, 2020).
ulcerative colitis (continued). "Further study indicated that EHLJ7 could cooperate with butyrate to exert its anti-ulcerative colitis effect by inhibiting the activation of janus kinase 2 (JAK2)/signal transducer and activator of transcription 3 (STAT3)/suppressor of cytokine signaling 1 (SOCS1) pathway." (PMID 32038241, 2019).
thyroid cancer (84 papers, 2012 to 2026). "In this study, we used a meta-analysis to systematically evaluate the relationship between STAT3 protein expression and the susceptibility and clinicopathological characteristics of thyroid cancer." (PMID 35463085, 2022). "In this study, we conducted a meta-analysis to evaluate the relationship between the expression of STAT3 protein and thyroid cancer susceptibility and its clinicopathological characteristics." (PMID 35463085, 2022). "Based on the collected data, we established that STAT3 protein expression is strongly related to thyroid cancer susceptibility, lymph node metastasis, tumor size, and TNM stage." (PMID 35463085, 2022). "This study reveals that STAT3 protein expression is significantly related to the susceptibility and clinicopathological characteristics of thyroid cancer." (PMID 35463085, 2022). "In summary, our meta-analysis systematically analyzed the relationship between STAT3 protein and thyroid cancer susceptibility and clinical progression." (PMID 35463085, 2022). "STAT3-mediated signaling is often associated with aberrant proliferation and therapeutic resistance of thyroid cancer cells." (PMID 32182833, 2020). "A recent report demonstrated that constitutive STAT3 activation can be mediated via the IL-6/gp130/JAK autocrine signaling pathway in different thyroid cancer lines that express RET/PTC, B-RafV600E, or mutated Ras." (PMID 24662939, 2014). "Results indicated that high expression levels of STAT3 protein increase the risk of thyroid cancer." (PMID 35463085, 2022). "Activation of STAT3 pathway was implicated in progression of thyroid cancer." (PMID 35543351, 2022). "IL6, an important cytokine, has been shown to mediate diverse biological functions including normal cellular growth and immune response through activation of STAT3 while its aberrant secretion is known to associated with the pathogenesis of various human diseases including thyroid cancer." (PMID 31936675, 2020). "Furthermore, recently, a role of activated interleukin 6 (IL-6)/STAT3 signalling has been reported in driving the resistance of BRAF-mutated thyroid cancer cells to vemurafenib, and the blockade of the IL-6 or STAT3 axis has been proposed to increase vemurafenib activity." (PMID 36979673, 2023). "Furthermore, a meta-analysis incorporating eight studies, encompassing 448 thyroid cancer patients and 227 controls, revealed a significant correlation between STAT3 protein expression and susceptibility to thyroid cancer, as well as clinical-pathological characteristics." (PMID 37671970, 2023). "Curcumin can target the signal transducer and activator of transcription 3 (STAT3) to synergistically enhance the anticancer activity of cisplatin in thyroid cancer cells." (PMID 41059296, 2025). "highlighted the effect of the STAT3 inhibitor S3I‐201 on the progression of thyroid cancer induced by a high‐fat diet (HFD)." (PMID 40620232, 2025). "By analyzing microarray data from the GEPIA database, we also found that POSTN levels were positively correlated with STAT3 and IL-4 is strongly linked to STAT6 in thyroid cancer." (PMID 38773979, 2024). "SIGLEC-15 is indicated as a new immune checkpoint for thyroid cancer since it acts as a putative oncogene, activating the STAT1/STAT3 signaling pathway to promote thyroid cancer cell growth, leading to an increase in immunosuppression." (PMID 38338696, 2024). "Overall these findings suggest that GDF15 is induced by mitochondrial stress in thyroid cancer cells and functions as a mitokine through downstream STAT3 activity to promote cancer progression." (PMID 36642986, 2023). "Previous studies had found that abnormal activation of STAT3 in human thyroid cancer specimens, and its overexpression had a strong correlation with the pathogenesis of thyroid cancer." (PMID 37660003, 2023).
thyroid cancer (continued). "The functions of JAK/STAT3 signaling discovered in our study were consistent with a previous finding that revealed the roles of JAK/STAT3 signaling in promoting thyroid cancer development in a transgenic tumor model." (PMID 36982542, 2023). "In our previous work on thyroid cancer, we found that Six1 activates the STAT3 signaling pathway via EYA1, resulting in increased expression of p-STAT3 and C-MYC." (PMID 38031089, 2023). "At the same time, when the cutoff value is set to >5%, compared with normal tissue, the expression of STAT3 in thyroid cancer tissue is also highly expressed (OR = 40.27, 95% CI (1.15, 1412.99), p = 0.042)." (PMID 35463085, 2022). "Results suggested that compared with normal tissue, the expression of STAT3 in thyroid cancer tissue is highly expressed (OR = 14.41, 95% CI (6.94, 29.91), p < 0.001)." (PMID 35463085, 2022). "As a result, the expression of STAT3 protein can be used as an indicator of the prognosis of patients with thyroid cancer." (PMID 35463085, 2022). "The current study exhibited an effective decrease of p-JAK2 and p-STAT3 protein levels upon oridonin treatment in thyroid cancer TPC-1 and BCPAP cells, as evidenced by western blotting." (PMID 35813296, 2022). "Results indicated that the expression of STAT3 protein in thyroid cancer tissue is highly expressed (OR = 14.41, 95% CI (6.94, 29.91), p < 0.001)." (PMID 35463085, 2022). "As expected, the protein levels of phosphorylated-JAK2 and phosphorylated-STAT3 were dramatically reduced upon oridonin treatment in thyroid cancer TPC-1 and BCPAP cells." (PMID 35813296, 2022). "We performed a meta-analysis to quantitatively evaluate the relationship between the expression of the STAT3 protein in thyroid cancer and its clinicopathological characteristics." (PMID 35463085, 2022). "In this study, meta-analysis was used to clarify the relationship between STAT3 expression and clinicopathological factors in thyroid cancer." (PMID 35463085, 2022). "For the analysis of STAT3 expression in thyroid cancer tissue and normal tissue, we conducted a sensitivity analysis and publication bias detection." (PMID 35463085, 2022). "In recent years, there have been several studies concerning the clinicopathological significance of the expression of the STAT3 protein in thyroid cancer." (PMID 35463085, 2022). "When the cutoff value is greater than 10%, the expression of STAT3 in thyroid cancer tissue is more highly expressed than normal tissue (OR = 13.10, 95% CI (5.85, 29.40), p < 0.0001)." (PMID 35463085, 2022). "STAT3/LINC00671/LDHA axis regulates thyroid cancer glycolysis, growth, and lung metastasis both in vitro and in vivo." (PMID 34404767, 2021). "Downregulated expression of TFF3 increases the expression of pSTAT3/STAT3, suggesting that the effect of TFF3 expression level on the occurrence of thyroid cancer is closely related to the expression of STAT3." (PMID 34567204, 2021). "Taken together, these results suggest that STAT3 increases proliferation, migration, and invasion of thyroid cancer cells and activates glycolysis via regulation of LINC00671 expression." (PMID 34404767, 2021). "Regarding thyroid cancer, miR‐1301‐3p was decreased in PTC tissues and suppressed thyroid cancer cell proliferation through the ABHD11‐AS1‐miR‐1301‐3p/STAT3 feedback loop based on J. Wen's study." (PMID 34268792, 2021). "Constitutively activated STAT3 plays a vital role in oncogenic manifestations in most human cancers, including thyroid cancer." (PMID 31936675, 2020). "The constitutive activation of Janus Kinase/Signal Transducer and Activator of Transcription (JAK/STAT) signal transduction is well elucidated in STAT3-mediated oncogenesis related to thyroid cancer and is considered to be a plausible therapeutic target." (PMID 31936675, 2020).